GCLM (glutamate-cysteine ligase modifier subunit)
Diseases named in the same sentence as GCLM in open-access papers (continued):
Sharing a sentence is not in itself a finding about the gene and the disease.
tumor (20 papers, 2015 to 2025). "Consistently, nuclear GCLM overexpression increased the xenograft tumor growth rate and weight in vivo." (PMID 39747101, 2025). "The results showed that the expression of NRF2, GCLM and GPX4 was increased in ESCC compared with adjacent non-tumor tissues, and the high expression of NRF2, GCLM and GPX4 was significantly associated with poor prognosis." (PMID 40707557, 2025). "Compared with the normal group, the expression of DDC and SYT11 were remarkably up-regulated in the tumor group, while the expression of GCLM, PSMB7, TYRO3, and AGMAT were remarkably down-regulated in the tumor group." (PMID 38526709, 2025). "GCLM was upregulated in a variety of human tumor types, and patients with the high level of GCLM mRNA had lower recurrence-free and overall survival rates." (PMID 37496661, 2023). "Applying RNA sequencing analysis in renal CAKI1 tumor cells to explore highly upregulated molecular signatures in response to hLcn-2, we identified a cluster of genes (SLC7A11, GCLM, GLS), which are implicated in regulating ferroptosis." (PMID 34069743, 2021). "Functionally, we show that NEDD4-mediated H3 ubiquitination, by transcriptionally activating IL1α, IL1β and GCLM, is important for tumour sphere formation." (PMID 28300060, 2017). "Target genes of glucose-induced H3 ubiquitination, such as interleukin (IL)-1α, IL1β and glutamate-cysteine ligase regulatory subunit (GCLM), are also important factors for tumour sphere formation." (PMID 28300060, 2017). "In addition, the expression level of GCLM is closely related to immune cell infiltration in the tumor microenvironment, which further affects tumor progression and patient prognosis." (PMID 40707557, 2025). "As we have already identified IL1α, IL1β and GCLM as important transcriptional targets of glucose-induced H3 ubiquitination, we investigated whether they are involved in tumour sphere formation." (PMID 28300060, 2017). "Six sEV proteins were identified, namely, GCLM, KEL, APOF, CFB, PDE5A, and ATIC, which properly distinguished normal control, early neoplasia, and advanced neoplasia patients from each other." (PMID 34589434, 2021). "To further explore our findings in a clinically relevant setting, we analyzed the hLcn-2-dependent target genes SLC7A11, GCLM, and GLS at mRNA level in either tumor tissue or adjacent healthy tissue of 32 patients diagnosed with clear cell RCC (ccRCC)." (PMID 34069743, 2021). "This pattern of enrichment in AC and SCC was also seen with the other NRF2 target genes, GCLC, GCLM and NQO1, although HMOX1 was downregulated in both tumour types." (PMID 27824809, 2016). "The results showed that the expression levels of NRF2, GCLM and GPX4 were significantly increased after intervention with RT + Fer-1 or RT + TBHQ compared with the RT group in tumor tissues of the two ESCC cell lines, and there were statistical differences in all of them." (PMID 40707557, 2025). "The RT‐PCR results demonstrated that mRNA expression levels of SLC7A11, SLC1A5, and GCLM were notably up‐regulated and SAT1 was down‐regulated in HCC patients' tumor tissues compared with their ANLTs, which were consistent with the results from TCGA database analysis." (PMID 35841206, 2023). "The present study identified six sEV proteins, namely, GCLM, KEL, APOF, CFB, PDE5A, and ATIC, that could distinguish early neoplasia, advanced neoplasia, and normal controls from each other well." (PMID 34589434, 2021). "In order to verify whether SLC7A11, GCLM, and GLS are specifically induced by iron-loaded Lcn-2, we stimulated CAKI1 tumor cells with iron-free, apo-Lcn-2 (aLcn-2) and a mutant form (mLcn-2) deficient of its iron binding capacity compared to hLcn-2." (PMID 34069743, 2021). "Consequently, accumulation of Nrf2 leads to aberrant activation of ARE-driven cytoprotective genes (e.g., HO-1, GCLM, NQO1) in so much as to shelter or promote Nrf1α−/−-driven tumor cells." (PMID 30562963, 2018).
tumor (continued). "Because Nrf2D29H still promoted tumor initiation in the absence of GSR, it is likely that this is due to expression of GCLC and GCLM, Nrf2 targets that promote GSH synthesis." (PMID 40334547, 2025).
infection (4 papers, 2017 to 2025). The state of being infected such as from the introduction of a foreign agent such as serum, vaccine, antigenic substance or organism. "Finally, GCLM, which has been shown to be essential to erythrocyte survival during oxidative stress and whose deficiency is associated with hemolytic anemia, was also upregulated during infection." (PMID 34399690, 2021). "The results demonstrated that ASFV-WT infection suppresses key genes involved in the Nrf2 signaling pathway, including GCLM, GCLC, Keap1, and NFE2L2 (Nrf2)." (PMID 39964001, 2025). "Examination of the mRNA expression of key enzymes in the glutathione synthesis pathway displayed a marked increase (p < 0.05) in glutamate cysteine ligase (GCL) subunits GCLc and GCLm, glutathione synthetase, and glutathione reductase during the infection." (PMID 28725637, 2017). "The expression levels of GCLc and GCLm, the subunits of the glutamate cysteine ligase (GCL), are significantly increased by P. gingivalis infection at 6 and 24 h of infection even in the presence of ATP." (PMID 28725637, 2017).
cardiovascular disease (3 papers, 2017 to 2025). "Obtained data supplement the earlier studies on important functional role of GCL enzyme, depending on expression of GCLC and GCLM genes, in cardiovascular disease development." (PMID 28757675, 2017). "Future studies relating arterial smooth muscle redox, GCLc, and GCLm function may provide useful insight into how calcification is induced and maintained, revealing novel therapeutic targets in cardiovascular disease." (PMID 41441180, 2025).
GCLM also shares sentences with these, for which no sentence is quoted: colon cancer (2 papers); endothelial dysfunction (2); esophageal squamous cell carcinoma (2); neurodegenerative disease (2); acute kidney injury (1); adenocarcinoma (1); adenoma (1); age-related macular degeneration (1); alcoholic liver diseases (1); allergic disease (1); cardiac hypertrophy (1); chronic kidney disease (1); chronic obstructive pulmonary disease (1); colorectal adenocarcinoma (1); glioma (1); Hyperglycemia (1); influenza (1); kidney cancer (1); liver (1); lung adenocarcinoma (1); lymph node metastasis (1); myocardial infarction (1); neurological disorders (1); nonalcoholic steatohepatitis (1); Obesity (1); preeclampsia (1); renal carcinoma (1); rheumatoid arthritis (1).